NEDD4L (NEDD4 like E3 ubiquitin protein ligase)
Diseases named in the same sentence as NEDD4L in open-access papers (continued):
Sharing a sentence is not in itself a finding about the gene and the disease.
breast carcinoma (21 papers, 2009 to 2025). "Cytoplasmic yes-associated protein 1 (YAP1) promotes autophagic death in breast cancer cells, and NEDD4L mediates ubiquitination and downregulation of YAP1." (PMID 38027016, 2023). "Several studies found that NEDD4L was probably implicated in the anticancer or cancer-promoting effects of some substances in breast cancer." (PMID 34869021, 2021). "Interestingly, NEDD4L downregulation in breast cancer was found to be caused through the action of a microRNA (miR-106b-25)." (PMID 35204725, 2022). "More interestingly, re‐introducing WT, but not the enzyme‐inactive variant Nedd4l‐C962A, could inhibit AKT phosphorylation in NEDD4L‐depleted breast cancer cells, coupled with decreased CTR1 protein levels." (PMID 34278744, 2021). "While some of the top candidates have been previously reported to play a role in cancer (FLNB, MAP3K7, NFYA, and ESYT2) others were identified to be breast cancer-relevant for the first time (NEDD4L, MARK2, ABI1)." (PMID 38664594, 2024). "CircKDM4B suppressed the progression of breast cancer via the inhibition of miR-675-mediated targeting of NEDD4L." (PMID 37568787, 2023). "In breast cancer, miR-675-upregulated NEDD4L can catalyze the ubiquitination of PI3KCA, thereby inhibiting VEGFA secretion and ultimately inhibiting blood vessel formation." (PMID 38027016, 2023). "CD71, a transferrin receptor, is an important mediator of ferroptosis, and its degradation, mediated by NEDD4L via the ubiquitin–proteasome system, inhibits ferroptosis in breast cancer cells after exposure to ionizing radiation." (PMID 38027016, 2023). "After exposure of breast cancer cells to ionizing radiation, interactions between NEDD4L and SLC7A11 increase, followed by SLC7A11 ubiquitination and degradation, ultimately inducing ferroptosis in breast cancer cells." (PMID 38027016, 2023). "Previous studies confirmed that SFN inhibited TGF-β1-induced migration and invasion in breast cancer cells and NEDD4L expression significantly reduced in breast invasive carcinoma." (PMID 36980857, 2023). "The C-terminus of forkhead box O1 (FOXO1) is downregulated by NEDD4L via ubiquitination at K463 site, which inhibits breast cancer stem cells." (PMID 38027016, 2023). "One study showed that circKDM4B sponged miR-675 to upregulate NEDD4L expression, thus inhibiting breast cancer progression." (PMID 38027016, 2023). "CTR1 is abnormally elevated in breast cancer, and NEDD4L downregulates CTR1 via ubiquitination to inhibit the PDK1-AKT pathway." (PMID 38027016, 2023). "NEDD4L was shown to suppress tumorigenesis of breast cancer by degrading copper transporter 1 (CTR1) and subsequently inhibiting Akt signaling." (PMID 37580757, 2023). "In brief, most research suggests that NEDD4L suppresses the malignant biological behavior of breast cancer cells, and further studies are necessary to discover its underlying mechanism in breast carcinogenesis." (PMID 34869021, 2021). "Dexamethasone was reported to promote the lung metastasis of breast cancer by regulating the PI3K-SGK1-CTGF pathway through the NEDD4L-Smad2 axis." (PMID 34869021, 2021). "For the first time, we elucidated that ESR1 and NEDD4L functioned together after radiation treatment and finally induced ferroptosis in breast cancer cells, which provides novel insight into the guidance of clinical treatment of breast cancer." (PMID 35252218, 2021).
breast carcinoma (continued). "A study reported that ERα could prevent ferroptosis in breast cancer cells that had been exposed to ionizing radiation, and this was achieved through the NEDD4L/CD71 pathway." (PMID 38383297, 2024). "Another study showed that NEDD4L could be directly inhibited by the miR-106b-25, which mediated breast cancer initiation by activating NOTCH1 signaling." (PMID 38027016, 2023). "Another study reports that in breast cancer cells, expression of the miR-106b-93-25 cluster results in NEDD4L down regulation and subsequent stabilization of Notch1, a direct target of NEDD4L ubiquitination; Notch1 is generally overexpressed in GBM and is linked to lower overall survival." (PMID 36552827, 2022). "We observed that the mutations/deletion of NEDD4L was mutually exclusive with the activation of AKT signaling pathway (PTEN deletion/mutations, epidermal growth factor receptor (EGFR), PI3KC, or AKT1 mutations/amplification) in breast cancers." (PMID 34278744, 2021). "In various breast cancer cells, miR-106b-25 could inhibit the expression of NEDD4L to upregulate the level of NOTCH1, which was instrumental in tumor-initiating cell (TIC) induction." (PMID 34869021, 2021). "Moreover, the miR‐106b‐25 cluster mediated oncogenesis in breast cancer by activation of NOTCH1 by targeting NEDD4L in both ER+ and TNBC breast cancer cells, suggesting that the miR‐106b‐25/NEDD4L/NOTCH1 axis played a crucial role in breast cancer." (PMID 32249490, 2020). "Out of the validated genes, we are specifically interested in HECT-domain type E3 ligase NEDD4L, since the altered expression of this gene has been shown to affect cancer progression in a wide range of cancer types including breast cancer, glioma, non-small cell lung cancer and prostate cancer." (PMID 26130719, 2015). "Although previously thought to target mostly ion channel proteins rather than signalling pathways, NEDD4L (also known as NEDD4-2) has been linked to NOTCH1 down regulation in breast cancer cell lines, and high NEDD4L expression is associated with longer breast cancer relapse-free periods." (PMID 35204725, 2022). "All three microRNAs were upregulated and repressed NEDD4L, EP300, and SMAD7 in breast cancer, influencing epithelial–mesenchymal transition, tumoral transformation, and therapy response." (PMID 40943553, 2025). "NEDD4L mediates the ubiquitination and downregulation of PI3KCA, inhibiting breast cancer and glioma cell migration and invasion in vitro." (PMID 38027016, 2023). "Another study reported that ESR1 enhanced the binding of NEDD4L to CD71, promoted CD71 ubiquitination and degradation, and inhibited ionizing radiation-induced ferroptosis in breast cancer cells." (PMID 38027016, 2023). "In support of an oncogenic role for CTR1, the authors find that CTR1 is abnormally elevated in breast cancer, and is subjected by NEDD4 like E3 ubiquitin protein ligase (Nedd4l)‐mediated negative regulation through ubiquitination and subsequent degradation." (PMID 34278744, 2021). "In contrast, in ER+ breast cancer cells lacking Orai3 overexpression, Sek-1 phosphorylates NEDD4L, subsequently inducing its inactivation via sequestration of the 14-3-3 protein." (PMID 38027016, 2023). "Mechanistically, TRIB3 can facilitate breast cancer stem cells through regulating AKT to interfere with the FOXO1-AKT interaction and inhibit FOXO1 phosphorylation, ubiquitination, and degradation by E3 ligases SKP2 and NEDD4L." (PMID 37732314, 2023). "miR-106b-25 negatively regulated NEDD4L and enhanced the levels of NOTCH1 in breast cancer cells." (PMID 37568787, 2023). "NEDD4L has been identified as an E3 ligase that mediates the ubiquitination and downregulation of PIK3CA, the catalytic subunit of class IA PI3Ks, thereby inhibiting the PI3K-AKT signaling pathway and VEGFA secretion in breast cancer." (PMID 38027016, 2023).
breast carcinoma (continued). "In keeping with this finding, we examined a panel of breast cancer cell lines, and found that the expression of Nedd4l, but not Nedd4, a close member of Nedd4l, seemed like to negatively correlate with AKT phosphorylation, especially with AKT‐pT308." (PMID 34278744, 2021).
glioma (21 papers, 2015 to 2024). A benign or malignant brain and spinal cord tumor that arises from glial cells (astrocytes, oligodendrocytes, ependymal cells). "More importantly, NEDD4L is downregulated in glioma cells, which is linked to aggressiveness and poor prognosis of malignant glioma." (PMID 36052751, 2022). "In addition, it has been reported that the downregulation of NEDD4L is associated with the progression and malignance of glioma." (PMID 36618071, 2022). "Similarly, in gliomas, reduced NEDD4L expression was associated with aggressive progression and worse prognoses, suggesting that NEDD4L could be a tumor suppressor that inhibits tumorigenesis." (PMID 31805126, 2019). "MiR-10b-5p promoted the M2 polarization of macrophages and enhanced the oncogenic phenotype of glioma cells through the downregulation of NEDD4L." (PMID 37568787, 2023). "Ubiquitination of the tumor oncogene sphingosine kinase 2 (SphK2) mediated by NEDD4L overexpression inhibits glioma cell viability and invasion as well as promotes glioma cell apoptosis." (PMID 38027016, 2023). "It downregulates NEDD4L expression, ultimately reducing the sensitivity of glioma cells to temozolomide." (PMID 38027016, 2023). "In gliomas, ubiquitination of sphingosine kinase 2 (SphK2) by NEDD4L was shown to suppress invasion of cells via blocking the AKT/β-catenin pathway." (PMID 37580757, 2023). "Another study reported that IGF-1-enhanced miR-513a-5p reduced the sensitivity of glioma cells to temozolomide by targeting the NEDD4L-downregulated Wnt/β catenin pathway." (PMID 38027016, 2023). "NEDD4L also enhanced the sensitivity of glioma cells to temozolomide by inhibiting Wnt/β-catenin signaling." (PMID 38027016, 2023). "The IGF-1-induced upregulation of miR-513a-5p considerably reduced the expression of NEDD4L in glioma cells." (PMID 37568787, 2023). "In glioma cells U251 and U87, overexpression of NEDD4L significantly reinforced the cytotoxic effects induced by the natural compound paeoniflorin (PF), accompanied by inhibition of cell viability and induction of ferroptosis." (PMID 37211949, 2023). "In human gliomas, the expression of NEDD4L is reduced, and patients with glioma who have low NEDD4L expression have a worse prognosis." (PMID 36293239, 2022). "By analyzing the cells, array, and RNA sequencing data of TCGA glioma patients, we found that NEDD4L is expressed at a relatively low level in gliomas." (PMID 36618071, 2022). "Hypoxic glioma‐derived EVs harboring upregulated miR‐10b‐5p triggered an M2 phenotype in macrophages as well as enhanced aggressive tumor biology of glioma cells via inhibition of PIK3CA/PI3K/AKT pathway by targeting NEDD4L." (PMID 36052751, 2022). "To verify this observation, we examined the expression level of NEDD4L in another glioma cell line U87 upon the treatment of PF." (PMID 36618071, 2022). "Taken together, these data imply that NEDD4L carries out its effect on glioma by manipulating STAT3, which appears to be the downstream factor for the signaling pathway." (PMID 36618071, 2022). "In summary, miR‐10b‐5p delivered by hypoxic glioma‐derived EVs accelerated macrophages M2 polarization to promote the progression of glioma via NEDD4L/PIK3CA/PI3K/AKT axis." (PMID 36052751, 2022). "Pearson correlation analysis revealed inverse correlation between miR‐10b‐5p and NEDD4L in glioma samples." (PMID 36052751, 2022). "Previous studies have demonstrated that low NEDD4L expression in non-small cell lung cancer, gastric cancer and gliomas is correlated with poor prognoses, while NEDD4L overexpression promotes melanoma tumor growth." (PMID 35236820, 2022). "In order to further validate this observation, we generated NEDD4L-knockdown (shNEDD4L) U87 glioma cell lines using three independent shRNAs targeting NEDD4L." (PMID 36618071, 2022). "miR‐10b‐5p delivered by hypoxic glioma‐derived EVs accelerated macrophages M2 polarization to promote the progression of glioma via NEDD4L/PIK3CA/PI3K/AKT axis." (PMID 36052751, 2022).
glioma (continued). "In order to explore the potential roles of NEDD4L in glioma, we first compared the expression of NEDD4L in 168 cancer samples and 5 normal tissue from the TCGA database." (PMID 36618071, 2022). "First, we found that NEDD4L expression levels were decreased in glioma cells compared with normal brain cells, whereas SphK2 expression was the opposite." (PMID 34305532, 2021). "Cell viability assay, flow cytometry assay, and transwell invasion assay were performed to illustrate the roles of NEDD4L-mediated SphK2 ubiquitination in glioma viability, apoptosis, and invasion, respectively." (PMID 34305532, 2021). "Compared with SphK2 overexpression alone, in combination with NEDD4L and SphK2, overexpression reversed SphK2-mediated promotion of glioma viability and invasion." (PMID 34305532, 2021). "Compared with the vector, overexpression of NEDD4L suppressed glioma U251 cell viability and invasion, while SphK2 overexpression promoted glioma cell viability and invasion." (PMID 34305532, 2021). "The results of flow cytometry assay also showed that NEDD4L abolished the inhibition of glioma cell apoptosis and death mediated by SphK2." (PMID 34305532, 2021). "The ubiquitination of SphK2 mediated by NEDD4L negatively regulated glioma malignancy via the AKT/β-catenin pathway." (PMID 34305532, 2021). "Ubiquitination of SphK2 mediated by NEDD4L overexpression suppressed glioma cell viability and invasion but promoted glioma apoptosis." (PMID 34305532, 2021). "NEDD4L overexpression repressed glioma proliferation and invasion and promoted glioma apoptosis via the SphK2/AKT/β-catenin pathway in vitro and in vivo." (PMID 34305532, 2021). "Overexpression of NEDD4L promoted glioma apoptosis, while NEDD4L knockdown inhibited glioma apoptosis." (PMID 34305532, 2021). "Taken together, all these results supported our findings that NEDD4L-mediated SphK2 ubiquitination functioned as a tumor suppressor in gliomas." (PMID 34305532, 2021). "In the present study, we showed that NEDD4L overexpression inhibited glioma cell viability and invasion." (PMID 34305532, 2021). "Overexpression of NEDD4L inhibited glioma cell viability and reversed IGF-1-repressed TMZ cytotoxicity." (PMID 31805126, 2019). "To explore the role of NEDD4L in regulating glioma cell death, we first cloned NEDD4L cDNA into pCDH vectors." (PMID 31805126, 2019). "Taken together, IGF-1-mediated miR-513a-5p upregulation significantly inhibited NEDD4L expressions in glioma cells." (PMID 31805126, 2019). "A previous study reported that downregulation of NEDD4L is observed in human gliomas, and patients with lower NEDD4L levels had poor prognoses." (PMID 31805126, 2019). "NEDD4L expression fluctuated from strong to weak as the pathological grade of gliomas increased." (PMID 38027016, 2023). "Ubiquitination of STAT3 by NEDD4L induces its downregulation in glioma cells." (PMID 38027016, 2023). "In addition, the downregulation of NEDD4L can promote M2 macrophage polarization, leading to tumor progression in glioma." (PMID 38027016, 2023). "In addition, paeoniflorin induces ferroptosis in human glioma cells by increasing NEDD4L-dependent STAT3 ubiquitination." (PMID 38027016, 2023). "In addition, our data demonstrated that forced expression of NEDD4L inhibits glioma cell growth probably by inducing ferroptosis, characterized by intracellular ROS accumulation and suppressed expression of the key factors in ferroptosis such as Nrf2 and GPX4." (PMID 36618071, 2022). "Taken together, this study demonstrates that PF can function as an antitumor agent for glioma treatment by targeting NEDD4L-dependent STAT3 ubiquitination as well as by regulating the Nrf2/GPX4 signaling axis, which might trigger ferroptosis." (PMID 36618071, 2022). "In addition, PF promotes the expression of NEDD4L in a time-dependent manner in glioma cells as well." (PMID 36618071, 2022). "We identified reduced NEDD4L expression in brain tissues from glioma." (PMID 36052751, 2022).